IL4 (interleukin 4)
Diseases named in the same sentence as IL4 in open-access papers (continued):
Sharing a sentence is not in itself a finding about the gene and the disease.
Obesity (continued). "In leptin-deficient or leptin-resistant HFD models, circulating levels of IL-4 decrease, leading to metabolic abnormalities like obesity, hyperglycemia, IR, liver injury, and changes in AKT, STAT3, and STAT6 pathways." (PMID 41007770, 2025). "Preclinical and early clinical research has explored pharmacological strategies to modulate IL-4 and IL-5 in obesity and metabolic dysfunction." (PMID 41007770, 2025). "The decreased IL-4 production by eosinophils in ATs of patients with obesity have decreased eosinophil number, low IL-4 production and hyperleptinemia." (PMID 40592472, 2025). "Like mast cells, eosinophils protect against obesity by regulating thermogenesis through the actions of IL-4 and IL-13." (PMID 41007770, 2025). "Several clinical studies highlight increased body mass index as a protective factor through the immunomodulatory effect of obesity secondary to increased serum levels of interleukins with an anti-inflammatory role (IL-4, IL-13)." (PMID 40002559, 2025). "Supplementation with IL-4 improves obesity, restores molecular pathways, and promotes browning of white adipocytes in epididymal tissue and a 3T3-L1 cell line." (PMID 41007770, 2025). "Although IL-4 and IL-13 share receptor components and overlapping signaling pathways, their roles in obesity-related adipose tissue fibrosis are still unclear." (PMID 41007770, 2025). "Recent experimental studies have investigated the role of IL-4 as a modulator of key metabolic and inflammatory pathways involved in the development of obesity." (PMID 41007770, 2025). "Our cohort with obesity also displayed hyperleptinemia and reduced levels of IL-4, a cytokine important for AT metabolic homeostasis, mostly released by EOS in AT." (PMID 38206766, 2024). "This is accompanied by a reduction in circulating IL-4 levels and decreased IL4 mRNA levels in the SVF of patients with obesity." (PMID 38206766, 2024). "The levels of IFN-γ, IL-4 and IL-10 in two undernutrition infected groups were higher than those in normal + infection and obesity + infection groups, while the results of TNF-α and IL-12 p70 were not different among the groups." (PMID 38185681, 2024). "Just one study examined IL-4 changes after the use of probiotic in obese rats; in this study, the IL-4 level was significantly increased and consequently, reduced the prevalence of obesity in rats after using Multi-strain probiotics." (PMID 38504163, 2024). "We next evaluated plasma levels of IL-4, which was found to be reduced in patients with obesity and IR compared with lean patients (BMI ≥ 30 kg/m2 [11.4 ± 2.0 pg/mL] versus BMI < 25 kg/m2 [23.3 ± 5.3 pg/mL], P = 0.05)." (PMID 38206766, 2024). "The higher transcription of mRNA FOXP3 and IL-10 (Treg markers), accompanied by a high transcription of TBX21 and IFNG (Th1 markers), GATA3 and IL-4 (Th2 markers) indicated the inflammatory status in the group with obesity and an altered Treg function." (PMID 37215211, 2023). "Further, iNKT-induced M2 polarization has been reported following acute or prolonged HFD challenges in an IL-4-dependent manner in mouse models and in human subjects with obesity." (PMID 37720534, 2023). "Logistic analysis after adjusting for sex, age, hypertension, obesity, and interleukin (IL)-10, IL-4, and IL-6 levels." (PMID 36160136, 2022). "The results imply that IL-4 counteracts the obesity-derived metabolic abnormalities, including DIO-induced CRMP2 expression." (PMID 35203376, 2022). "The attenuation of DIO-induced s-CRMP2 by IL-4 further verifies our inference that CRMP2 activity is elevated during the process of developing obesity." (PMID 35203376, 2022). "Elevated concentrations of some inflammatory cytokines are seen in obesity, such as interleukin 4 (IL-4), monocyte chemoattractant protein 1 (MCP-1), IL-6, and TNF-α." (PMID 36295052, 2022).
Obesity (continued). "Logistic analysis revealed that after adjusting for sex, age, hypertension, obesity, as well as IL-10, IL-4, and IL-6, an increased plasma level of TNF-α was significantly associated with sarcopenia (P < 0.001)." (PMID 36160136, 2022). "HF diet feeding augmented ex vivo IL-4 secretion by splenocytes, white adipose tissue (WAT) inflammation, and the severity of obesity-associated sequelae — the latter dependent on IL-4Rα-driven STAT6 activation." (PMID 34302121, 2021). "In the current report, beige adipocytes in transplanted SAT were required for IL4 induction among T cells in the meninges and choroid plexus, even after accounting for increases in T-cell number with dietary obesity." (PMID 34330904, 2021). "Zucker rats with obesity displayed a renal decrease of NO−, gene expression of eNOS, and anti-inflammatory cytokines, such as IL-10 and IL-4." (PMID 34621463, 2021). "Another example are IL-4-induced alternatively activated macrophages, which help to suppress inflammatory signals as they become down regulated in hyperinsulinaemia and obesity." (PMID 33922802, 2021). "Thus, according to other studies that also found an increase in IL-4 associated with obesity, we speculate that increased expression of IL-4 in the obese groups compared to lean subjects may be due to a compensatory mechanism trying to maintain cell functions, homeostasis and tissue integrity." (PMID 35069589, 2021). "Cytokine production by T cells remained essentially unchanged with pregnancy and pregravid obesity except for enhanced Th2 responses (IL-4+ CD4 T cells)." (PMID 34195568, 2021). "The results of GSEA based on immunity and immunology showed that the level and status of immune cells such as macrophages, CD4 + T cells, CD8 + T cells, and B cells have changed during the progress of obesity, which also involves cytokines such as IL-4." (PMID 34712134, 2021). "Interleukin-4 (IL-4) and IL-13 signaling via IL-4Rα regulates adipose tissue lipolysis, insulin sensitivity, and liver fibrosis in obesity." (PMID 34302121, 2021). "The decrease in the concentration of Th2 cells observed in obesity results in a decrease in the concentration of anti-inflammatory cytokines, such as interleukin 4 (IL-4), interleukin 5 (IL-5), interleukin 10 (IL-10) and interleukin 13 (IL-13)." (PMID 34564433, 2021). "A course of 8-week IL-4 supplementation improves common phenotypes of obesity and impaired signaling pathways of Akt, STAT3, and STAT6 in the hypothalamic, hepatic, and epididymal fat tissues." (PMID 32585823, 2020). "In the context of obesity, IL-4 expression and secretion are down-regulated, and suppression of IL-4 signaling suppresses beige adipogenesis in SAT and decreases whole body thermogenesis." (PMID 32452515, 2020). "In summary, Fas-mutant mice are resistant to high-fat diet-induced obesity due to increased IL-4 and IL-10 levels and the promotion of thermogenic protein activity and browning in their adipose tissues." (PMID 32686763, 2020). "The results of this study showed that obesity with sepsis exhibited more pronounced percentages of IL-4- and IL-17-expressing Th cells than did obesity alone." (PMID 33223959, 2020). "Despite some limitations of our experiments and some inconsistency with the literature, our results suggested that the Th2 cytokine IL-4 is a metabolic regulator and antiobesity candidate for the treatment of obesity and its complications." (PMID 32585823, 2020). "In randomized controlled trials, curcumin supplementation reduced serum IL-1β and IL-4 in adults with obesity (1 g/d for 8 wk) and reduced serum IL-6, MCP-1, and TNF-α concentrations in subjects with metabolic syndrome (1 g/d for 4 wk)." (PMID 32211803, 2020). "Studies on mice have shown that overexpression of IL-13 prevents high-fat diet-induced weight gain without affecting food consumption, and administration of IL-4 increased brown fat mass and the thermogenic capacity to decrease established obesity." (PMID 32962676, 2020).
Obesity (continued). "Since obesity is associated with lower circulating levels of IL-4, our current findings further highlighted IL-4 being an alternative candidate in combating obesity and its complications." (PMID 32585823, 2020). "By combining the findings from our serial reports, the contour of IL-4 in regulating energy metabolism, and therefore, the process from getting obesity, insulin resistance and diabetic onset is addressed." (PMID 31427606, 2019). "Meanwhile, obesity-induced insulin resistant status with long-term IL-4 overexpression was also established by feeding IL-4-injected mice with HFD (HFD + IL-4 mice)." (PMID 31814802, 2019). "Regulatory T-cells represent more than half of all CD4+ T-cells in lean murine adipose tissue, and in obesity, regulatory T-cells accumulate around macrophages, produce IL-4 and IL-10, and promote Th-2 T-cell polarisation." (PMID 29479350, 2018). "The helminth-induced immune responses mainly stem from the Th2 mediated cytokines IL-4, IL-10 and IL-13, the functions of which in nutrient metabolism and obesity are not fully understood and are an area of active research." (PMID 29545532, 2018). "In this study, we found that in obesity, the hyperinsulinemia presumably downregulates MΦ Irs2 expression, resulting in impaired IL-4-induced M2a-subtype MΦ activation, and consequently, development of inflammation and insulin resistance in the liver and WAT." (PMID 30451856, 2018). "Recently, CD11b showed unexpected role in obesity-induced insulin resistance by limiting the proliferation and alternative activation of adipose tissue macrophages (ATMs) by inhibiting the IL-4/STAT6 signaling pathway." (PMID 30356719, 2018). "The recent data show that IL-6 exhibits anti-inflammatory properties during obesity by promoting IL-4-dependant alternative macrophage polarization thus contributing to attenuation of obesity-induced inflammation and regulation of glucose homeostasis." (PMID 29163240, 2017). "Taken together, the direct functional significance of IL1RA and IL4 VNTRs particularly on affected tissues in obesity (like adipose tissue) and other metabolic disease (like type 2 diabetes mellitus) warrants further investigation." (PMID 28293435, 2017). "Studies on IL-4 in obesity suggest that eosinophils participate in the development of obesity-induced IR." (PMID 29387059, 2017). "Given the increased incidence of metabolic disorders resulting from the genetic ablation of Th2 or M2 inducers (e.g., Il4, Il13, Il33, Stat6, or Pparg), the decreased whole-body Th2/M2 status resulting from Pla2g5 deficiency may also contribute to the exacerbation of obesity-associated inflammation." (PMID 29259680, 2016). "Because loss of GRIP1 impaired M(IL4) polarization and function in vitro, we evaluated the role of myeloid GRIP1 in the systemic metabolic homeostasis in a diet-induced obesity model of insulin resistance." (PMID 27464507, 2016). "The pro-inflammatory cytokines TNFα, IL-1β, and IL-6, considered as highly involved in obesity-related IR and the anti-inflammatory cytokines IL-4 and IL-10 displayed similar levels in CT, OIS, and OIR subjects." (PMID 27111539, 2016). "Nevertheless, recent findings in the field laid a foundation for potential clinical application of IL-4 and Metrnl to treat metabolic diseases such as obesity and diabetes in humans." (PMID 26688684, 2015). "The insulin resistant proinflammatory states of obesity and type 2 diabetes are characterized by an increase in IL-4, MMP-9, LIGHT, and CCR-2 expression in MNC and MMP-9 and NOM concentrations in plasma." (PMID 25642424, 2015). "In conclusion, in patients with obesity and type 2 diabetes, insulin infusion leads to a suppression of the expression of IL-4, ADAM-33, LIGHT, and LTBR in parallel with a reduction in plasma NOM, TGFβ, MCP-1, and MMP-9 concentrations." (PMID 25642424, 2015). "IL-4 and IL-13 are able to generate a M2-state and disrupting M2 activation leads to obesity and IR." (PMID 25781614, 2015).
Obesity (continued). "In participants with general obesity, levels of IL-4, IL-10 and IL-13 were significantly elevated in participants with low physical activity, even when controlled for BMI which was negatively associated with physical acitivity." (PMID 25781614, 2015). "In contrast, obesity-resistant SWR mice exhibited an increased spleen potential for lymphocytes to produce greater levels of IL-4 and depressed potential for production of proinflammatory cytokines." (PMID 20877574, 2010). "Similarly, IL‐10 expression, an anti‐inflammatory cytokine, was suppressed by obesity, while IL‐4 levels remained unchanged across groups." (PMID 41549510, 2026). "However, in obesity, IL-4 and IL-13 have been found to have significant metabolic effects that are not yet fully understood." (PMID 41007770, 2025). "Since endogenous CTRP6 expression in BMDMs is upregulated by M1 polarization inducers, it may further hinder inflammation resolution, even in the presence of IL-4 during tissue repair, establishing it as a key driver of adipose tissue inflammation in obesity." (PMID 41159061, 2025). "However, due to its shared receptor pathways and functional similarities with IL-4, it warrants further exploration as a potential therapeutic target in obesity." (PMID 41007770, 2025). "IL-4 plays a crucial role in fat tissue metabolism and leptin secretion regulation, further linking immune system dysregulation to metabolic disturbances in obesity." (PMID 41007867, 2025). "While WAT fibrosis is associated with AT dysfunction in obesity, the direct contribution of IL-4 to this process has not yet been definitively established." (PMID 41007770, 2025). "In rats with obesity induced by monosodium glutamate, an elevation of proinflammatory cytokines IL-1β and IL-12B p40 was registered, coupled with downregulation of the anti-inflammatory system, as evidenced by reduced IL-4, IL-10, and TGF-β levels." (PMID 40259921, 2025). "The intestinal nematode H. polygyrus could protect against obesity by triggering the production of Th2-mediated cytokines, such as IL-4, lL-10 and IL-13, and enhancing the anti-inflammatory M2 macrophages levels." (PMID 40708918, 2025). "Treatment that reduces obesity symptoms could reduce epidermal thickness and eosinophil/mast cell infiltration, along with a reduction in IgE, IL-4, IL-6, TNF-α, and AD-like lesions." (PMID 39564133, 2024). "Moreover, IL-4 was also elevated in obese patients, suggesting the participation of IL-4 in the process of diet-induced obesity and metabolism." (PMID 36982747, 2023). "Research indicates that obesity significantly induces the production of pro-inflammatory adipokines, while adipose tissue secretes corresponding anti-inflammatory cytokines (such as IL-4, IL-10, IL-13, IL-19)." (PMID 38138996, 2023). "Th2-type cytokines such as interleukin 4 (IL4) promote the differentiation of M2 macrophages and thereby control multiple physiological processes ranging from immune modulation in obesity, cardiovascular diseases and type 2 diabetes to wound healing and tissue regeneration." (PMID 36610795, 2023). "Specifically, through use of eosinophil-deficient mice or transgenic mice that have increased eosinophils, these studies demonstrate that eosinophils produce IL-4 to promote M2 macrophages, which in turn mediate adipose tissue beiging and other protective pathways against obesity." (PMID 37162190, 2023). "Obesity has a strong association with immune cell abnormalities, and adipose tissue produces and releases various adipokines (leptin, adiponectin, resistin and visfatin) and pro-inflammatory cytokines (TNF-α, IL-4, IL-6)." (PMID 36574392, 2022). "In particular, OTU479 and OUT545 were significantly positively correlated with the percent of epididymal fat weight, TG, TC, LDL and TNF-α, and negatively correlated with IL-10, and IL-4 levels, revealing that their changes were closely connected with changed obesity in rats." (PMID 35807812, 2022).
Obesity (continued). "It is well known that a decrease of NFATC2 expression is associated with a reduction of the expression of cytokines in T cells, in particular IL-2, IL-3, IL-4 and TNF-alpha; the latter, in particular, is a pro-inflammatory cytokine associated with obesity and insulin resistance." (PMID 35159548, 2022). "After adjusting for sex, age, hypertension, blood lipid concentration, and obesity, the analysis of covariance revealed that the levels of IL-10, IL-4, and TNF-α in the case group were significantly higher than those in the control group (P < 0.001, P = 0.011, and P < 0.001, respectively)." (PMID 36160136, 2022). "Furthermore, after adjusting for sex, age, hypertension, obesity, and IL-10, IL-4, and IL-6 levels, an increased TNF-α level was also significantly associated with sarcopenia." (PMID 36160136, 2022). "Pro-inflammatory cytokines, such as TNF-α and IL-6, could contribute to systemic insulin resistance or metabolic disorder in obesity, while anti-inflammatory cytokines, such as IL-10 and IL-4, could prevent diet-induced obesity and insulin resistance." (PMID 35807812, 2022). "Therefore, we next investigated the impact of pregravid obesity on macrophage polarization potential using in vitro differentiation of monocytes collected at T3 using IFNγ (M1 like) and IL-4 (M2 like) conditioning." (PMID 34195568, 2021). "Moreover, due to the transformation of M2 macrophages to M1 in obesity tissues, the expression of anti-inflammatory cytokines IL-10 and IL-4 secreted by M2 macrophages is decreased." (PMID 34194325, 2021). "As the IL-4Rα is a shared receptor for IL-4 and IL-13, altered IL-13 levels in obesity might also play a role." (PMID 34302121, 2021). "Together, these findings amplify the complexity of the IL-4 axis in modulation of obesity and highlight the possibility that observed divergent effects may be dietary substrate driven." (PMID 34302121, 2021). "Moreover, metabolic syndrome and obesity are related to increased pro-inflammatory and decreased anti-inflammatory cytokines’ levels, including IL-4 and IL-10." (PMID 34199832, 2021). "IL-4 is a Th2 cytokine that can promote M2 macrophage polarization in adipose tissues, and it has been proposed that IL-4 signaling could be a potential target to sustain insulin sensitivity in obesity." (PMID 32585823, 2020). "Sirt6-mediated regulation of microenvironmental conditions in WAT, such as type 2 cytokine IL-4 production by adipocytes, may play important roles in protecting against obesity and insulin resistance." (PMID 31113929, 2019). "However, the underlying mechanisms by which M2a-subtype macrophage activation by IL-4 was impaired in obesity remain poorly understood." (PMID 30451856, 2018). "For TNFα and IL4, the primary contributing factor to population differences was higher obesity in AA women and higher education in EA women, respectively; whereas for IL1RA, obesity, education, and age at first childbirth were contributing factors to observed differences." (PMID 29879116, 2018). "For instance, data suggest that eosinophils may actually maintain adipose tissue homeostasis during obesity via IL-4 mediated promotion of alternative M2 polarization in tissue macrophages." (PMID 28771483, 2017). "Specifically, anti-inflammatory cytokines interleukin- (IL-) 13, IL-4, and IL-10 stimulate the alternatively activated ATMs (M2) in lean persons, while obesity induces a shift to the classically activated ATMs (M1) due to stimulation by proinflammatory cytokines TNF-α, IL-1β, and IL-6." (PMID 28293435, 2017). "Increased amounts of IL-4 in obesity may contribute to a more sustained production of antibodies, involved in the formation of immune complexes, and/or auto antibodies." (PMID 28243360, 2017). "The presence of higher values of IL4 and IL13 in obese patients may suggest that obesity is associated with a more anti-inflammatory cytokine expression during critical illness." (PMID 26064774, 2015).